ASCL1 (achaete-scute family bHLH transcription factor 1)
Diseases named in the same sentence as ASCL1 in open-access papers (continued):
Sharing a sentence is not in itself a finding about the gene and the disease.
tumor (continued). "Clinically, tumor tissue immunohistochemistry (IHC) staining is used to measure the protein expression of four transcription factors (ASCL1, NEUROD1, POU2F3, and YAP1) to identify SCLC subtypes." (PMID 40285610, 2025). "In one patient resected with R0 margin, the persistence of ASCL1 methylation preceded tumor recurrence by 4 months." (PMID 40567599, 2025). "Patient tumor samples co-expressing ASCL1 and NEUROD1 suggest that SCLC-A cells are derived from highly dedifferentiated normal NE cells, while SCLC-AN cells, which co-express both transcription factors, exhibit a higher degree of differentiation." (PMID 41220942, 2025). "Co-expression of POU2 F3+/YAP1+ within a tumor has been described as the second most common combination following ASCL1+/NEUROD1+." (PMID 40500731, 2025). "The dual role in proliferation and differentiation that ASCL1 plays in development has been shown in tumours too, making ASCL1 both an oncogene and a tumour suppressor." (PMID 40527452, 2025). "First, we performed immunostaining for ASCL1 and NEUROD1 on SCLC tissue samples, collected from the primary tumour site, of 15 patients between 2019 and 2022, and observed that 14 samples were positive for ASCL1." (PMID 40595415, 2025). "Research employing CODEX and Visium spatial multi-omics technologies demonstrated that tumor regions with a high MPTC signature, characterized by co-expression of ASCL1 and NEUROD1, were linked to poor patient prognosis." (PMID 41220942, 2025). "The results showed significantly lower tumor volume and weight in the sh-ASCL1 group compared to the sh-NC group." (PMID 39963143, 2025). "ASCL1 plays multiple oncogenic roles in BC, influencing tumor immunity, drug sensitivity, and cellular behaviors such as proliferation, migration, invasion, and EMT." (PMID 39963143, 2025). "The master transcription factor ASCL1 is indispensable for pulmonary neuroendocrine cell differentiation, and targeted disruption of Ascl1 has been shown to abrogate tumour formation in a mouse model of SCLC." (PMID 40595415, 2025). "By contrast, mesenchymal subtype tumours, which are enriched for astrocyte and injury-like signatures, generally lack ASCL1." (PMID 40527452, 2025). "In the context of SCLC, ASCL1 has been described to mediate Wnt signaling, thereby influencing NE differentiation, tumor cell proliferation and promoting epithelial-like characteristics through E-cadherin expression." (PMID 40165271, 2025). "Longitudinal single‐cell transcriptome analyses of SCLC tumours revealed the role of MYC‐mediated activation of Notch signalling in facilitating the transformation of ASCL1‐positive SCLC to a non‐NE YAP1‐positive state." (PMID 40847555, 2025). "Conversely, Ascl1-OE GFP+ tumor cells had a significantly higher percentage of EdU+ cells at P30 (15%) and terminal stage (12%) compared to control and/or the single CKO tumors." (PMID 39609428, 2024). "As predicted, double CKO (dCKO) of both Ascl1 and Olig2 prevented tumor formation in approximately 80% of TNP-deleted mice (N = 16/20, 4 litters), while 20% developed slow-growing tumors that were not lethal until 4-6 months of age." (PMID 39609428, 2024). "Co-localization analysis of ASCL1 and OLIG2 double+ cells in terminal tumors showed that while only 64% of OLIG2+ tumor cells are ASCL1+, 86% of ASCL1+ tumor cells were OLIG2+." (PMID 39609428, 2024). "In contrast, Ascl1-OE significantly increased the percentage of OLIG2+ tumor cells in both P30 (89%) and terminal (87%) tumors compared to controls (dark green bars)." (PMID 39609428, 2024). "By 8–10 weeks, primary and metastatic tumor cells were mostly AR− and ASCL1+ with heterogenous KRT8 and E-cadherin expression." (PMID 39394434, 2024). "Next, PGC-1α was overexpressed specifically in POU2F3/ASCL2 and ASCL1 PARCB tumor-derived cell lines, and its effects on OXPHOS activity and neuroendocrine differentiation were measured." (PMID 39589879, 2024).
tumor (continued). "We next analyzed how the lineage composition of tumor cells was altered in Ascl1-OE versus control tumors." (PMID 39609428, 2024). "Surprisingly, Zfp36l1 is upregulated in Ascl1-OE tumor cells, especially in qNSC and aNSC assigned cell types, likely because it is a target of ASCL1." (PMID 39609428, 2024). "In the ASCL1 tumor subtype, there was a notable enrichment of transcription factors coactivated by PGC-1α, including HNF4A and PPPARA, which were among the top 10 most significantly enriched." (PMID 39589879, 2024). "The platform is amenable to multiplexed gene editing at the time of tumor initiation, allowing us to establish the critical role of ASCL1 in NE transformation in a matter of months (versus 1–2 years required for multigenic crosses using GEMMs)." (PMID 39394434, 2024). "In contrast, only 36% of control tdTOM+ tumor cells were ASCL1+ at P30, which then increased to 54% at terminal stages." (PMID 39609428, 2024). "Lymph node metastases showed prominent exclusion of CD45+ cells within ASCL1+ tumor nests, highlighting the capacity of NEPC to promote immune exclusion within lymphocyte-dense microenvironments." (PMID 39394434, 2024). "A decrease in immune infiltration was also observed in NEPC regions of a prostatectomy specimen from a patient with mixed PRAD/NEPC histology, with CD11c+;CD68+ TAMs present within ASCL1+ tumor areas." (PMID 39394434, 2024). "In both control and Ascl1-OE tumors, approximately 90% of the tumor cells were assigned a CNS cell type (OPC, NFOL, MOL, qNSC, aNSC, or astrocyte), while the remaining 10% were assigned a microglia cell type, the majority of which are found in cluster #5." (PMID 39609428, 2024). "Thereafter, synthesized analysis of both SCLC cell lines and tumor RNA data further suggested that SCLC can be definitively distinguished by the TFs ASCL1, NEUROD1, YAP1 and POU2F3." (PMID 39103941, 2024). "Conversely, Psenen, Tbcb, and Tmem147 are three of the top downregulated DEGs that were highly expressed in control tumor cells but were drastically reduced across Ascl1-OE tumor cells." (PMID 39609428, 2024). "Other studies have suggested that originally high ASCL1-expressing tumours evolved to create a subclone high in NEUROD1 and low in ASCL1." (PMID 39682746, 2024). "To address this, we compared the cell type and migration of newly induced control versus Ascl1-OE tumor cells at P4." (PMID 39609428, 2024). "Conversely, the immunofluorescent levels of OLIG2 were lowered in Ascl1-OE tumor cells compared to Ascl1-CKO tumor cells." (PMID 39609428, 2024). "Achaete-scute homolog 1 (ASCL1) is a powerful player in modulating neuroendocrine differentiation in tumor cells." (PMID 38315310, 2024). "Perturbation of this interaction attenuates the expression of pivotal genes, such as ASCL1, and impedes tumor proliferation." (PMID 39103941, 2024). "Degarelix treatment increased the fraction of NEPC tumor area and ASCL1+ tumor cells and decreased the fraction of AR+ tumor cells relative to vehicle treated RPM SQ tumors." (PMID 39394434, 2024). "Compared to control, Ascl1-OE tumor cells showed a 3-fold decrease in oligodendrocyte lineage cell types, with OPCs (4%) decreasing by 10-fold while both NFOL (11%) and MOL (11%) each showed a 6% decrease." (PMID 39609428, 2024). "Analysis of cellular immunofluorescent intensity of GFP+ tumor cells confirmed that the level of ASCL1 was elevated by about 2-fold compared to control or Olig2-CKO tumor cells." (PMID 39609428, 2024). "PGC-1α overexpression promoted tumor growth only in the ASCL1 subtype, with responses varying from a twofold to fivefold increase in tumor volume." (PMID 39589879, 2024). "Three of the top upregulated and most highly expressed DEGs in the majority of Ascl1-OE tumor cells are Tmsb4x, Sparcl1, and Mt3." (PMID 39609428, 2024).
tumor (continued). "Similar to SC53, there was a strong positive correlation between A2 and E scores both in all cells in the tumor and in ASCL1+ cells, whereas the correlations between other subtypes’ scores and E scores were either significantly weaker or negative." (PMID 36900269, 2023). "Iadademstat (ORY-1001) is an LSD1 inhibitor in phase 2 clinical trials in leukemia (NCT05546580) that has been shown to reactivate Notch signaling, thereby suppressing ASCL1 activity and reducing tumor growth in SCLC mouse models." (PMID 38203275, 2023). "ASCL1 expression was detected in the nucleus of tumor cells in all cases, with high expression (≥50%) in 76.2% of SCLCs and 77.8% of type I LCNECs." (PMID 38126617, 2023). "BCL2 has already been proposed as a therapeutic target as its pharmacological inhibition stops ASCL1‐dependent tumor growth." (PMID 35263037, 2022). "In SCLC, ASCL1 activates neuroendocrine differentiation and regulates stemness, cell cycle progression, and mitosis, thus maintaining tumor development and survival." (PMID 35220975, 2022). "Whereas the vast majority of SHH-1B [10/12 (83%)] stained positive for ASCL1 (> 5% of tumor cells), positive ASCL1 staining was less frequent in SHH-1A [7/23 (30%) and SHH-2 [9/21 (43%); Chi-Square: 9.044; P = 0.01]." (PMID 35501487, 2022). "It is identified that malignant cells in lymph‐node metastatic SCLC have inter‐patient and intra‐tumor heterogeneity characterized by distinct ASCL1 and NEUROD1 expression patterns." (PMID 36618022, 2022). "In a tumor weakly positive for ASCL1 (SCLC-20, NE score -0.05), the ASCL1-high regions were found to be more classic-like whereas the ASCL1-low regions were more variant-like." (PMID 33750914, 2021). "We next analyzed the snRNA-seq to identify the tumor cells that express ASCL1 and NEUROD1, and then integrated this data set with the scATAC-seq using SEURAT34." (PMID 34599169, 2021). "It was observed that an elevated expression of ASCL1 induced production of serum ProGRP, thus favoring the neuroendocrine differentiation of tumor cells." (PMID 33809582, 2021). "The neuroblastoma dependency factor MEIS2, together with ASCL1, was identified as a candidate tumor-initiating factor and shown to be a novel core regulatory circuit member in adrenergic neuroblastomas." (PMID 34638267, 2021). "According to a recent study, MYC can act as a master regulator for NE-differentiation and can dynamically shift tumor phenotype acting on the NOTCH signaling pathway from ASCL1 + NEUROD1+ (NE-high) to YAP1+ or POU2F3+ (NE-low)." (PMID 34200100, 2021). "The integrated scATAC analysis of FLM3 and FLM5 revealed that 99% of the FLM5 tumor cells overlap the FLM3 ASCL1 cluster, indicating that those cells have identical chromatin accessibility." (PMID 34599169, 2021). "Within the same tumor, areas with low tumor ASCL1 levels exhibited more CD8+ and CD4+ T cell infiltration, whereas areas with high tumor ASCL1 levels showed fewer CD8+ or CD4+ T cells." (PMID 33750914, 2021). "By applying Spearman's rank‐ordered correlation (>0.4) to RNA‐seq of the 164 TCGA GBM samples, we then identified the top 10% of genes that showed a positive correlation with ASCL1 expression across these tumor samples." (PMID 32573857, 2020). "The aim was to analyse the tumor expression of Notch1, Hes1, Ascl1, and DLL3in Small-Cell Lung Cancer (SCLC) and each such biomarker’s potentialassociation with clinical characteristics and prognosis afterplatinum-doublet chemotherapy (PDCT)." (PMID 33104707, 2020). "CgA and the transcription factor ASCL-1, along with other neuroendocrine biomarkers, are often used to assess tumor burden and response to therapy." (PMID 33114525, 2020). "Similar to the early tumors and the PDX‐GBMs, ASCL1, OLIG2, and SOX2 were coexpressed in the tumor cells of these terminal tumors, and many ASCL1+ tumor cells were also Ki67+." (PMID 32573857, 2020).
tumor (continued). "Compared with mice transplanted with cells transduced with LentiCRISPRv2-GFP encoding a control sgRNA, animals xenografted with ASCL1 and SOX11 gene-edited cells survived longer, which was associated with reduced tumor PDGFRA expression at endpoint." (PMID 32142668, 2020). "In ASCL1High SCLC and NE-NSCLC, knockdown of ASCL1 induces cell death, suggesting the role of ASCL1 for tumor cell survival." (PMID 31324758, 2019). "The importance of ASCL1 in NE tumour survival does, however, highlight the potential vulnerability of tumours heavily dependent on ASCL1." (PMID 31836808, 2019). "The overall migration and invasion properties of GBM CSCs in vitro were also affected by ASCL1 overexpression, with CSCs progressing from single cell-driven to homotypic collective invasion and migrating as compact clusters of tumor cells." (PMID 30538287, 2019). "The recurrent tumour showed a 70–80 fold increase of expression of transcription factors ASCL1 and HOXA1 and tyrosine kinases FGFR3, HER3, HER4 and MET." (PMID 31747973, 2019). "With the passage of time, it seems likely that tumor cells change into an ASCL1 (low)/NEUROD1 (high) expression pattern which is coincident with the appearance of variant morphology phenotype in GEMMs." (PMID 30477547, 2018). "Conversely, tumours with low ASCL1 and LMO4 expression had better prognosis, matching the cell line results in which these genes were downregulated by RA." (PMID 28187790, 2017). "Although ASCL1 seemed to be expressed across a number of NB primary tumours, we next verified this in a panel of NB cell lines both at the mRNA and protein level." (PMID 25786414, 2015). "We undertook this by analysing the expression of NA markers that we characterised in Xenopus AVNA development (Ascl1, Hand2, Phox2a and TH) in NB primary tumours, using publicly available microarray data." (PMID 25786414, 2015). "Ascl1 is only expressed transiently in AVNA differentiation, whereas NB tumours and almost all NB cell lines have high levels of ASCL1 expression, indicating that NB cells are stalled at this transient stage of NA neuron development." (PMID 25786414, 2015). "We then investigated ASCL1 expression in a number of human neural-derived tumours, again using publically available microarray data." (PMID 25786414, 2015). "We evidenced a recurrent low-level copy number gain including the locus of ASCL1 in almost all the tumor samples we examined, especially in the CIS." (PMID 23114535, 2012). "An inverse relation of ASCL1 to DKK1 expression was observed in 68% of the analysed tumours (n = 22)." (PMID 19744316, 2009). "An inverse relation of ASCL1 to DKK1 protein expression was observed for 15 out of 22 tumours (68%)." (PMID 19744316, 2009). "It has been demonstrated that combining ASCL1 with markers such as OTP, HNF1A or CD44 improves NETs subclassification, with identifying groups linked to clinical characteristics, including patient sex and tumor location." (PMID 41196447, 2025). "ASCL1 expression correlates with the tumour‐initiating capability of SCLC." (PMID 40847555, 2025). "Concordant OTP and ASCL1 expression profiles were observed in all tumor tissues from each patient." (PMID 41196447, 2025). "TTF-1 and ASCL1 cooperatively promote neuroendocrine differentiation and tumor growth." (PMID 40437627, 2025). "We next asked whether LATSi can reverse the fully established NEPC tumor phenotype that develops in vivo by establishing ASCL1+ tumoroids from NEPC tumors that developed following orthotopic transplantation of RPM and TKO organoids." (PMID 41509338, 2025). "Instead, a group of SCLC tumours was identified with low expression of ASCL1, NEUROD1 and POU2F3." (PMID 39567755, 2025). "Similarly, ASCL1‐OE reduced proliferation in vitro and tumour growth in vivo in mouse KRASG12C‐mutant LUAD cells (H and S15D‒H)." (PMID 41025426, 2025).
tumor (continued). "Given that the involvement of ASCL1 in neuroendocrine differentiation and tumor progression suggests that it may be a key driver for the emergence of NEPC." (PMID 40165961, 2025). "Hence, LSD1 inhibitors (e.g., ORY-1001) and histone deacetylase (HDAC) inhibitors such as pracinostat have demonstrated potential in preclinical models by downregulating ASCL1 and suppressing tumor growth." (PMID 40333678, 2025). "Interestingly however, in one patient resected with R0 margin, the persistence of ASCL1 methylation preceded tumor recurrence by 4 months." (PMID 40567599, 2025). "Notably, SCLC tumour cells expressing ASCL1 and NEUROD1 exhibit neuroendocrine features whereas those expressing YAP1 and POU2F3 exhibit a neuroendocrine low phenotype." (PMID 39567755, 2025). "Compared to other molecular subtype CDXs (14 ASCL1 CDXs, 4 NEUROD1 CDXs, and 4 ATOH1 CDXs), ATOH1 CDXs were the most aggressive, taking only 61 days to reach the target tumor volume of 800–1,000 mm2 compared to ASCL1 (75 days, p = 0.0128) and NEUROD1 (95 days, p < 0.0001)." (PMID 40305287, 2025). "Furthermore, ASCL1 overexpression facilitates prostate cancer progression and metastasis, while its inhibition reduces tumor cell proliferation." (PMID 39963143, 2025). "Interestingly, ASCL1 appeared to be a good predictor of cfDNA tumor fraction of individual patients." (PMID 40001151, 2025). "Gene expression analyses across these cell clusters confirmed that Ascl1/GFP, along with ASCL1 canonical NOTCH signaling target genes (Dll3, Notch1, Hes5) and the bHLH E-protein co-binding partners (Tcf4, Tcf12) were significantly elevated in Ascl1-OE tumor cells compared to control." (PMID 39609428, 2024). "Consequently, nuclear deprivation of ASCL1 and NEUROD1 via KPNB1 inhibition led to impaired growth of SCLC-A and SCLC-N tumor cells in vitro and tumor shrinkage of ASCL1-driven xenografts in vivo." (PMID 38395864, 2024). "Interestingly, however, the concomitant loss of ASCL1 in vivo in one study did not stop NE small cell tumour formation, suggesting a compensatory mechanism by other NE drivers; however, a similar in vivo study showed moderate tumour control by ASCL1 knockout." (PMID 39682746, 2024). "Thus, in the absence (Olig2-CKO) or presence of lower levels of OLIG2 (Ascl1-OE) within tumor cells, ASCL1 is able to escape this dimerization or repression to potently activate NSC/astrocyte genes." (PMID 39609428, 2024). "This implies that ASCL1’s role in conferring tumor cell migration within GBMs may utilize downstream mechanisms independent of RND3 function." (PMID 39609428, 2024). "Consequently, affected radial glia are then transformed into tumor-propagating NPCs marked by dynamic levels of ASCL1 and OLIG2." (PMID 39609428, 2024). "Furthermore, the ASCL1 tumor subtype had higher expression of both subunits of the mitochondrial pyruvate carrier, which allows entry of pyruvate into the mitochondrion to fuel OXPHOS." (PMID 39589879, 2024). "This dramatic migration was accompanied by a significant decrease in tumor cell density on the ipsilateral hemisphere and a 2- to 4-fold increase in migration distance on the contralateral corpus callosum compared to control and Ascl1-CKO tumors." (PMID 39609428, 2024). "Thus PGC-1α and ASCL1 are co-upregulated in multiple clinical tumor types with heightened SCN differentiation." (PMID 39589879, 2024). "ASCL1 KO impeded tumor development compared with control organoids." (PMID 39024561, 2024). "Indeed, ASCL1 overexpression in two PARCB POU2F3/ASCL2 tumor-derived cell lines led to increased PGC-1α expression in both cell lines." (PMID 39589879, 2024). "In a mouse model of ASCL1 subtype, Aurora A inhibition was shown to trap cells in mitosis, causing lower expression of ASCL1 gene and higher MHC-I and interferon target gene expression, suggesting the possibility with these drugs to switch from immuno cold to hot tumours." (PMID 39215193, 2024).